TNF (tumor necrosis factor)
Diseases named in the same sentence as TNF in open-access papers (continued):
Sharing a sentence is not in itself a finding about the gene and the disease.
Sepsis (continued). "In our study, serum levels of MLKL correlated with those of other proinflammatory cytokines such as TNF and suPAR, highlighting that elevated levels of MLKL might reflect the activation of immunological processes during sepsis disease." (PMID 29606984, 2018). "We also established a murine model of P. aeruginosa-induced sepsis using TREM2-deficient versus WT C57BL/6 mice, and found that TNF-α expression was comparable between the two groups (data not shown), which is consistent with our observation in this study." (PMID 29887864, 2018). "PCT and TNF-α are the important biomarkers of infection and inflammation, and elevated levels of PCT and TNF-α are usually related to the severity and poor prognosis of sepsis." (PMID 30046610, 2018). "Consistently, our data showed that IL-27 treatment significantly enhanced TNF-α and IL-6 secretion and apoptosis of THP-1 cells upon LPS stimulation, which further demonstrated that IL-27 is critical in the pro-inflammatory responses during sepsis." (PMID 30268141, 2018). "To evaluate if sepsis alters the function of naïve monocytes in a long-term manner, we stimulated MACS-sorted bone marrow monocytes with LPS and measured the production of TNF and IL-6." (PMID 30510555, 2018). "In the early stages of toll-like receptor 4- (TLR4-) mediated sepsis, SIRT1 rapidly accumulated at TNF-α and IL-1β promoter regions and deacetylated the RelA/p65 lysine 310 site and nuclear histone H4 lysine 16 sites, ultimately promoting NF-κB transcription termination." (PMID 30533222, 2018). "Thus, researchers have focused on TLR4/MEK/ERK/TNF-α signaling, with the aim of developing a method to prevent mitochondrial dysfunction and AKI induced by sepsis." (PMID 30092777, 2018). "In all patients with sepsis, serum tenascin-C was significantly positively correlated with SOFA score (P = 0.011), serum creatinine (P = 0.006), CRP (P = 0.001), IL-6 (P < 0.001) and TNF-α (P = 0.026)." (PMID 30442110, 2018). "Since macrophages with altered expression levels of TNFα, CCR2 and iNOS are expected to affect lung inflammation, homeostasis and host resistance, we determined the functional implication of NFATc3 deletion on sepsis-induced ALI in mouse CLP sepsis models." (PMID 29535830, 2018). "The observation of anti-TNF antibody being administered to baboons 2 h before an LD100 of Escherichia coli protecting them completely from harm is in sharp contrast to the uselessness of neutralizing TNF once clinical sepsis is underway." (PMID 29725287, 2018). "LPS or TNF alpha decreased PPAR gamma expression in adipose tissue, as seen in our model of sepsis." (PMID 30538802, 2018). "In this study, we showed that GSKJ4 protects mice against septic death and reduces the expression of inflammatory factors IL-1β, TNF-α, IL-6, and MCP-1 in vivo, suggesting that JMJD3 may be the key molecule driving early sepsis progression." (PMID 30337925, 2018). "Our results in the S. aureus sepsis model, demonstrated that TNF-α signaling through TNFR1 is not required for MDSC expansion and accumulation but it is critical for the expression of MDSC immunosuppressive mediators such as Arginase 1 and iNOS." (PMID 30123776, 2018). "The laboratory indicators used for the clinical diagnosis of sepsis include CRP, IL-6, IL-8, tumor necrosis factor-α (TNF-α) and PCT, none of which are ideal diagnostic indicators due to their deficiencies in diagnostic specificity and sensitivity." (PMID 29760745, 2018). "The inhibition of specific inflammatory cytokines such as a tumor necrosis factor (TNF), migration inhibitory factor (MIF), or high mobility group box (HMGB)-1 provided promising results in experimental sepsis, but, they failed in the clinical trials for sepsis." (PMID 29780390, 2018).
Sepsis (continued). "We investigated if reduction in the serum concentration of the cytokines tumor necrosis factor α, interleukin (IL)-6 and IL-10, and the rate of change in the IL-6 level at 24 h after ICU admission were survival predictors for patients with sepsis and septic shock in a Vietnamese population." (PMID 30400775, 2018). "We also developed an immune assay to assess the effects of patient plasma on healthy monocyte-derived macrophage tumor necrosis factor (TNF) production because monocyte deactivation is a key feature of AD/ACLF and reduced monocyte TNF production predicts poor outcomes in sepsis." (PMID 28911947, 2018). "In contrast, the levels of TNFα did not significantly change from pre-sepsis to during sepsis in either group." (PMID 30555806, 2018). "To determine a causal relationship between the decreased ILC2 in the lungs and increased MLEC death in Il-33−/− mice following sepsis, we co-cultured ILC2 with mouse MLEC in vitro in the presence and absence of LPS and TNFα, which mimic sepsis stimulation." (PMID 29511181, 2018). "In our previous studies, we also found that 5-HT could increase the production of TNF-α and IL-6 in MODS, sepsis, and PPA formation." (PMID 29849496, 2018). "TNF-α is key sepsis mediator and is increased in circulation following LPS administration; thus, the serum decrease of TNF can have an important role in the sepsis outcome." (PMID 30524657, 2018). "Several studies demonstrate that the protective role of MSCs in sepsis may be attributed to the soluble paracrine factors released by these cells, such as interleukin (IL)-10, prostaglandin E2 (PGE2), tumor necrosis factor (TNF)-α and IL-6." (PMID 29273091, 2017). "In patients with septic AKI, the levels of TNF-α, IL-1β, IL-6, IL-2sR and IL-10 were significantly increased, while the levels of IL-8 was significantly decreased compared with sepsis patients without AKI." (PMID 28296904, 2017). "In addition, enhanced sepsis severity was also demonstrated by Scr (kidney injury), ALT (liver injury) and cytokines (TNF-α, IL-6 and IL-10) at 18h post-CLP." (PMID 28750040, 2017). "Moreover, significant lower levels of TNF-α, IL-6, bacterial loads, MPO, and ROS were discovered in the KO-CLP sepsis group in contrast to the WT-CLP sepsis group." (PMID 28694565, 2017). "We investigated the effects of 24 h delayed normobaric oxygen (NBO2) and HBO2 treatment on the endogenous production of the inflammatory markers interleukin (IL)-6, tumor necrosis factor (TNF)-α and IL-10, and on mortality in rats with cecal ligation and puncture (CLP) induced sepsis." (PMID 29204105, 2017). "In contrast, higher day 1 levels of TNF-α, IL-6, IL-8, and CRP (p = 0.013, p < 0.001, p = 0.001, and p = 0.017, respectively), but not IL-1β (p = 0.057), were observed in patients with septic shock compared with those with severe sepsis." (PMID 28542440, 2017). "TNF-α, Il-1β, and IL-6 are not considered to be “gold standard” biomarkers of sepsis due to their short half-life." (PMID 28367457, 2017). "In accordance to our results TNFα responsiveness and HLA-DR protein expression correlated positively and were lowest in non-survivors of sepsis." (PMID 28771573, 2017). "In summary, our data demonstrated that IRE1-NF-κB pathway was obviously activated by ER stress during sepsis and contributed to the septic AKI through enhancing the production of pro-inflammatory cytokines (TNF-α, IL-1β and IL-6) in the renal proximal tubular epithelial cells." (PMID 28430592, 2017). "Clinical trials with a TLR4 antagonist and TNF-α inhibitor have shown no improvement of the mortality rate of severe sepsis patients; however, those trials did not examine long-term muscle function." (PMID 28742154, 2017). "TNF-α had estimated means of 1.44 pg/mL for patients with sepsis, and 4.6 (P = 0.16) for nonseptic patients, also with no significant temporal variation." (PMID 28769538, 2017).
Sepsis (continued). "We evaluated the effects of sepsis serum with or without TNF-α, EGF, EGF receptor inhibitor or exosomes of sepsis sera treated NF on human keratinocyte (HaCaT) proliferation (BrdU assay), viability (MTT assay), and migration (horizontal wound healing model)." (PMID 28086962, 2017). "Moreover, among sepsis patients, the rs1024611 AG/GG and rs2857656 GC/CC carriers exhibited significant increases in expression levels of MCP-1 (P = 0.025), TNF-α (P = 0.034) and IL-6 (P = 0.043) compared with the rs1024611 AA or rs2857656 GG carriers." (PMID 28472164, 2017). "The other cytokines in our study (IL-1β, TNF-α, IL-12/23p40, IL-21, IL-17, G-CSF, and GM-CSF) do not appear to be useful markers for clinical decisions regarding sepsis." (PMID 28769538, 2017). "Interestingly, in a murine model of polymicrobial sepsis, inhibition of the PI3K pathway increased serum IL1-β, IL-6 and TNF-α levels and decreased the survival rate of septic mice." (PMID 28545453, 2017). "Indeed, TNF-α, IL-1β, IL-6 mRNA expressions in the kidney were found to be greatly enhanced at 6 hours after CLP which was regarded as the early stage of sepsis." (PMID 28430592, 2017). "The injection of rSj-Cys significantly reduced the production of inflammatory cytokines including TNF-α, IL-6 and IL-1β compared to mice with sepsis without treatment." (PMID 28482922, 2017). "HMGB1 is considered as a late mediator compared with the release of other cytokines, such as TNF and IL-1, in response to lethality during sepsis as well as after necrosis, but not apoptosis or death." (PMID 29440779, 2017). "This phenomenon is also observed in patients with sepsis, in whom plasma levels of TNF-α decline rapidly and therefore do not represent disease severity." (PMID 28054645, 2017). "We detected higher serum levels of cytokines TNF-α (5.7 vs. 0.7 pg/ml, P < 0.001), IL-6 (24.8 vs. 3.8 pg/ml, P < 0.001), IL-10 (30.0 vs. 11.9 pg/ml, P = 0.040), and VEGF (177.9 vs. 48.1 pg/ml, P = 0.018) in sepsis sera." (PMID 28086962, 2017). "Although the size of the spleen from T. gondii-infected mice was similar to naïve mice, after the induction of sepsis, T. gondii-infected mice experienced a notable reduction in spleen size along with a striking emergence of IFN-γ- and TNF-α-producing CD4+ and CD8+ T cells into the peritoneum." (PMID 28439500, 2017). "In both SM and sepsis, a variety of toxins triggers the activation of MAPK and NFκB signalling pathways to induce the release of host immune factors that include cytokines, such as TNF, IL‐6, IL‐1, oxygen free radical." (PMID 27042299, 2016). "Sepsis induced an increase in pro-inflammatory cytokines (TNF-α and IL-6) into the kidney, but there was no statistical difference between the LPS + FR and LPS + BT groups." (PMID 27993148, 2016). "The decrease of TNF production occurs without IL-10 increase, suggesting that the modulation of TNF release was not related to the overproduction of IL-10, as in sepsis-induced immunosuppression based on LPS tolerance." (PMID 27441846, 2016). "Tumor necrosis factor (TNF)-α is a pleiotropic cytokine with intense pro-inflammatory and immunomodulatory properties, and anti-TNF-α biologics are effective therapies for various inflammatory diseases such as inflammatory bowel disease (IBD) and sepsis." (PMID 27879679, 2016). "Among these studies were publications showing that antibodies to TNF would not improve sepsis survival which was published 3 years before the human studies demonstrated that TNF inhibitors were not effective." (PMID 27669150, 2016).
Sepsis (continued). "We also found that monocytopenia and defective production of tumor necrosis factor were associated with reduced formation of granulomas in patients with severe sepsis even if TNF did not seem to be involved in the defective granuloma formation." (PMID 27441846, 2016). "Specifically, we found that treatment with TRPV4 channel inhibitors reduced mortality in lipopolysaccharide (LPS) and cecal-ligation-and-puncture (CLP), but not in TNFα, models of sepsis in mice." (PMID 27653046, 2016). "Pharmacological inhibition of TRPV4 channels in mice reduced mortality in lipopolysaccharide and cecal-ligation-and-puncture models of sepsis, but not in a tumor necrosis factor-α (TNFα)-induced sepsis model." (PMID 27653046, 2016). "Sepsis induced serious inflammatory pathological injuries and increased potent pro-inflammatory cytokines TNF-α and IL-1β, which were suppressed by CORM-2, but not iCORM-2, intervention." (PMID 27144520, 2016). "TNF belongs to the tumor necrosis factor family and tumor necrosis factor-α (TNF-α) is the main member that has many functions including inflammation, sepsis, lipid and protein metabolism, haematopoiesis, angiogenesis and host resistance to parasites and malignancy." (PMID 27672514, 2016). "Sepsis compared to bacteremia (25.95 ± 68.32; P = 0.85) and to viremia (18.88 ± 22.64; P = 0.322) showed no significant changes in TNF-α serum concentrations." (PMID 26315105, 2015). "This small scale patient study could show that common sepsis markers PCT, CRP, IL6 and TNFα had low predictive value for early diagnosis of SIRS after cardiovascular surgery." (PMID 26263001, 2015). "The best OR values for sepsis diagnosis were obtained using PCT, MR-proADM, IL-6, and TNF-α." (PMID 26635427, 2015). "The failure of thrombopoiesis is an unlikely hypothesis to the degree that the plasma levels of IL-6, tumor necrosis factor (TNF)-α, and thrombopoietin are increased in sepsis." (PMID 25767472, 2015). "Although TNF-α plays an important role in sepsis-induced immunoparalysis, it is not the only factor involved in immunoparalysis." (PMID 25535255, 2015). "While CLP‐induced suppression was dependent on TNF activity, neither the activation of TNF receptors type 1 nor TNF receptor type 2 alone was sufficient to generate sepsis‐induced suppression showing that the two TNF receptors can substitute each other." (PMID 26734459, 2015). "All these results indicated that LPS-TLR4/TACE/TGF-α/EGFR/MAPKs represented a novel signal pathway by which LPS stimulates TNF-α production in cardiomyocytes and EGFR might be a potential therapeutic target for the treatment of endotoxemia or sepsis." (PMID 26486084, 2015). "Importantly, we found that among the subgroup of patients with severe sepsis, the rs653765 CC genotype carriers expressed significantly higher levels of CX3CL1, IL-6R and TNF-a than the CT/TT carriers." (PMID 25888255, 2015). "IL-6, CRP and TNF-α are common and sensitive but non-specific markers of inflammatory processes and increased concentrations are measured after trauma and in sepsis." (PMID 25609264, 2015). "Historically, severe systemic inflammation—that is, release of tumor necrosis factor (TNF), monocyte chemoattractant protein-1 (MCP-1), interleukin-6 (IL-6), and other inflammatory mediators—was thought to play the major role in sepsis-induced multiple organ dysfunction syndrome (MODS)." (PMID 25959381, 2015). "Interestingly, TNF and particularly TNFR2 have previously been shown to be involved in the development of Treg after sepsis." (PMID 26734459, 2015). "It is also significant that this dual blocker had no influence on TNF-α, IL-6 or IL-10 plasma levels, nor angiotensin II or aldosterone plasma concentration, in this model of sepsis." (PMID 25288367, 2015). "Use of anti-TNF antibody in mice subjected to CLP sepsis significantly reduced TNF-α bioactivity but interestingly did not reduce mortality." (PMID 26502877, 2015).
Sepsis (continued). "This retrospective investigation analyzed the role of the cytokines IL1-β, sIL-2R, IL-6, IL-8, IL-10 and TNF-α as potential markers for major post-transplant adverse events including VOD, skin and intestinal GvHD, sepsis as well as bacterial, viral and fungal infections in 61 pediatric patients." (PMID 26315105, 2015). "The predominance of high producer genotype of TNF-α with sepsis patients are not clear in this study." (PMID 26561011, 2015). "All these results indicated that dexmedetomidine can inhibit the generation of inflammatory mediators such as TNF-α and IL-6 during sepsis and this effect is independent of its α2-adrenoceptor activation effect." (PMID 25929655, 2015). "The distribution of haplotype of the TGF-β, TNF-α, IL-2, IL-4, IL-6 and IL-10 genes were studied in patients with sepsis and non-sepsis." (PMID 26561011, 2015). "We asked whether our M(IFNγ + LPS, TNFα) signature could be used to predict the complication of dengue infection into a hemorrhagic outcome, the drug response in HIV positive patients, and sepsis resolution in children." (PMID 26302899, 2015). "In Gram-negative sepsis IL-6 and TNF-α showed the best AUC values (both 0.93); in Gram-positive sepsis the best AUC was found for IL-6 (0.91); in yeast sepsis IL-6, IL-8, and IL-10 showed the highest AUC values (0.92 for all)." (PMID 26635427, 2015). "After Bonferroni correction, there was no significant decrease (P = 0.046) of TNF-α between sepsis (55.42 ± 63.04 pg/ml) and fungemia (13.37 ± 12.60 pg/ml)." (PMID 26315105, 2015). "TNFα production was also not impaired in GP33-stimulated responsive CD8+ T-cells from all SIRS/sepsis groups, confirming that SIRS or sepsis did not cause persistent defects in the antigen sparked cytokine response." (PMID 25541945, 2014). "Our observation that hMSCs can suppress IL-2, IL-6 and TNF but not IFNγ is consistent with a previous finding in which administration of mMSCs reduced serum levels of IL-6 and TNF but not that of IFNγ in a cecal ligation and puncture model of sepsis." (PMID 24423010, 2014). "The IL-2 induced toxicity shares many features with sepsis such as capillary leakage, systemic complement activation, and a relatively non-specific rise in inflammatory mediators such as TNF-alpha, C-reactive protein, and in advanced cases organ failure." (PMID 24884532, 2014). "CAM decreases the ratio of serum IL-10 to serum TNF-α in patients with ventilator-associated pneumonia (VAP) and sepsis caused by gram-negative bacteria." (PMID 24632748, 2014). "TNF-α, an important cytokine, has been shown to have no sufficiently predictive value for sepsis development after trauma." (PMID 27602370, 2014). "The cytokine effects of sepsis driving CMV viraemia have previously been described; it is appears that the presence of pro-inflammatory cytokines, tumour necrosis factor-alpha (TNF-alpha) and interleukin (IL)-1 beta in the early stages of sepsis reactivate CMV from latency." (PMID 25399401, 2014). "Our study contrasts those investigating effects of hemorrhagic shock and sepsis, as our experiment TNFα release was not significantly depressed after DHEA administration." (PMID 24886543, 2014). "In a murine model of sepsis, the high affinity orthosteric agonist, ATL313, decreases circulating plasma levels of pro-inflammatory cytokines and chemokines such as TNF-α, MIP-1α, MCP-1 and increases the plasma level of the anti-inflammatory cytokine IL-10 within 4 h of LPS injection." (PMID 25473378, 2014). "Although these findings correlate well with aspects of systolic myocardial dysfunction seen in sepsis, in this model, acutely, TNF-α does not appear to provide a cellular mechanism for sepsis-related diastolic myocardial dysfunction." (PMID 24303157, 2013). "In contrast, different strategies to inhibit TNFα in patients with sepsis revealed no overall benefit with regard to mortality reduction." (PMID 24236088, 2013).